FGF21 (fibroblast growth factor 21)
Diseases named in the same sentence as FGF21 in open-access papers (continued):
Sharing a sentence is not in itself a finding about the gene and the disease.
alcoholic liver diseases (9 papers, 2015 to 2025). A disorder caused by damage to the liver parenchyma due to alcohol consumption. "Further study is required to assess the therapeutic potential of FGF21 in the treatment of alcoholic liver disease." (PMID 29107287, 2017). "Taken together, these effects suggest the potential value of FGF21 as a therapeutic agent for alcoholic liver disease." (PMID 29107287, 2017). "By using global FGF21 knockout (KO), we demonstrate that FGF21 signaling is involved in the development/progression of experimental alcoholic liver disease." (PMID 27498701, 2016). "This suggests that FGF21 protects against long term ethanol induced hepatic damage and may attenuate progression of alcoholic liver disease." (PMID 29107287, 2017). "Some studies showed that FGF21 administration could ameliorate alcoholic liver disease in mice." (PMID 36457562, 2022). "Previous studies have found that FGF21 and KLB play an important role in the treatment of alcoholic liver disease." (PMID 40786112, 2025). "FGF21–ethanol dynamics are thought to confer protection against the development of alcoholic liver disease 22, 23; however, the effect of chronic alcohol consumption on FGF21 levels in humans has not been reported." (PMID 31687174, 2019).
colorectal cancer (9 papers, 2019 to 2026). A primary or metastatic malignant neoplasm that affects the colon or rectum. "FGF-21 also retained statistical significance in stage I–II colorectal cancer and in cases with samples collected more than 5 years before diagnosis." (PMID 33664295, 2021). "Since the result for FGF-21 was retained for colon cancer and stage I-II colorectal cancer in the validation dataset, the clinical differences between the two datasets do not seem to have affected the main findings." (PMID 33664295, 2021). "Suppressing miR-583 through hsa_circ_0001955/miR-583/FGF21 axis promotes colorectal cancer." (PMID 37158948, 2023). "In conclusion, we identified two markers (FGF-21 and PPY) that were associated with colon and rectal cancer respectively, suggesting a potential of biomarkers to discriminate between different subtypes of colorectal cancer." (PMID 33664295, 2021). "One notable exception was fibroblast growth factor 21 (FGF-21), elevated levels of which were associated with a higher risk of colorectal cancer in the Swedish study, in which both the discovery and validation phases used pre-diagnostic samples, and in the BliTz validation set." (PMID 34503217, 2021). "Notably, FGF-21 was associated with early, but not late, stages of colorectal cancer." (PMID 33664295, 2021). "Despite being potentially predictive and possibly related to colorectal cancer etiology, neither FGF-21 nor PPY would be useful as standalone biomarkers of colon or rectal cancer." (PMID 33664295, 2021).
hyperthyroidism (9 papers, 2014 to 2024). Overactivity of the thyroid gland resulting in overproduction of thyroid hormone and increased metabolic rate. "On the other hand, in adults with hyperthyroidism, the serum FGF-21 levels have been negatively associated with %BF." (PMID 34946319, 2021). "We also observed an independent association between FGF21 and elevated liver enzymes in hyperthyroidism." (PMID 30692965, 2018). "In model 3, with further adjustment with TG, TC, and hyperthyroidism, we found serum FGF21 levels remained independently associated with elevated ALT [1.42 (1.01–1.99), p < 0.043], but the significant association between serum FGF21 and elevated AST disappeared [1.23 (0.82–1.84), p < 0.318]." (PMID 30692965, 2018). "Therefore, the aim of our case-control study is to establish if there is an association between FGF21 and liver enzymes in hyperthyroidism." (PMID 30692965, 2018). "Therefore, it appears there is a possible association between FGF21 and impaired liver enzymes in hyperthyroidism." (PMID 30692965, 2018). "Although results of animal studies strongly suggest an interaction between FGF21 and thyroid hormones in humans, only limited and unambiguous data are available, as clinical studies found elevated FGF21 levels in both hyperthyroidism and hypothyroidism." (PMID 39452947, 2024). "A reduced level of FGF21 was reported in hypothyroidism, whereas an elevated FGF21 level was observed in hyperthyroidism." (PMID 37343156, 2023). "One person from the control group and one patient with hyperthyroidism were excluded because of the extremely high baseline serum FGF21 values exceeding the upper range of assay sensitivity." (PMID 35909532, 2022). "In these patients serum FGF21 levels were unchanged in hyperthyroidism as compared with euthyroidism." (PMID 35909532, 2022). "While FGF21 and leptin showed a decrease, ghrelin showed an increase with treatment of the hyperthyroidism." (PMID 35929907, 2022). "Our study provides for first time the clinical evidence for relevance of FGF21 and liver enzymes in hyperthyroidism." (PMID 30692965, 2018). "Our previous study in hyperthyroid patients also showed serum FGF21 levels were elevated in hyperthyroidism." (PMID 30692965, 2018). "So far there is no study in human being to determine the relationship between FGF21 and liver enzyme in hyperthyroidism." (PMID 30692965, 2018). "FT3 and FT4 correlated with FGF21 among patients with hyperthyroidism." (PMID 39452947, 2024). "The significant downregulation of KLB gene in TAO orbital adipose tissue will reduce the FGF21-induced fat catabolism, which may be one of the reasons for increased orbital adipose tissue in patients with hyperthyroidism." (PMID 37900130, 2023). "Thus, there is a consistent pattern suggesting that FGF21 is elevated in hyperthyroidism, with reduction after treatment." (PMID 35929907, 2022). "We found that serum FGF21 levels fell after the treatment of hyperthyroidism." (PMID 35929907, 2022). "In patients with hyperthyroidism, serum FGF21 concentration is positively correlated with liver enzyme concentrations, suggesting that serum FGF21 concentration is related to liver function impairment in patients with hyperthyroidism." (PMID 35369322, 2022). "The aim of this study was to assess the effect of hyperthyroidism and its treatment on body weight and composition, insulin resistance, and mediators of appetite and energy homeostasis, namely ghrelin, leptin, adiponectin, and FGF21." (PMID 35929907, 2022). "Furthermore, after reversal of hyperthyroidism, liver enzyme shared the similar change trend as that of FGF21." (PMID 30692965, 2018). "However, information is limited regarding serum FGF21 and impaired liver function in hyperthyroidism." (PMID 30692965, 2018). "However, in humans, FGF21 serum levels were unaltered in hyperthyroidism, as were insulin and glucose levels." (PMID 25172631, 2014).
hyperthyroidism (continued). "The aim of this study was to assess the effect of hyperthyroidism and its treatment on body weight and composition, insulin resistance, and mediators of appetite and energy homeostasis, namely ghrelin, leptin, adiponectin, and fibroblast growth factor 21 (FGF21)." (PMID 35929907, 2022). "Hence FGF21 may be a potential biomarker for liver function impairment or drug-induced liver injury in hyperthyroidism, which needed to be further investigated in the future." (PMID 30692965, 2018). "Compared to the normal subjects, patients with hyperthyroidism had significantly elevated serum liver enzymes, including alanine transaminase (ALT) (p < 0.001), aspartate aminotransferase (AST) (p < 0.001) levels, as well as FGF21 levels (p < 0.001)." (PMID 30692965, 2018). "Neither hyperthyroidism nor eprotirome treatment altered insulin, glucose, or FGF21 levels." (PMID 25172631, 2014). "Sixth, neither hyperthyroidism nor eprotirome treatment had an effect on the circulating FGF21." (PMID 25172631, 2014).
Infertility (9 papers, 2016 to 2023). "In rodents, FGF21 overexpression is shown to cause infertility, such as delayed vaginal opening, reduced mating, and anovulatory hypogonadism." (PMID 31817081, 2019). "A previous report showed that Fgf21 transgenic mice exhibit GnRH deficiency with infertility by repressing the vasopressin–kisspeptin pathway." (PMID 28754744, 2017). "This study indicated that the infertility observed in FGF21 overexpressing mice is due to the increased energy expenditure and the caloric deficit resulting from high FGF21 levels." (PMID 34517929, 2021). "Conversely, prior work observed that female mice with FGF21 overexpression were infertile via central suppression of kisspeptin signaling and GnRH release." (PMID 33135359, 2020). "Potential side-effects of these high FGF21 concentrations could be decreased bone mass and infertility in female mice." (PMID 30888399, 2019). "FGF21 overexpression causes infertility in female mice fed a chow diet, but when these mice are fed a high fat diet, fertility is restored without altering circulating concentrations of FGF21." (PMID 33808081, 2021).
liver cancer (9 papers, 2013 to 2025). An epithelial or non-epithelial malignant neoplasm that arises from the liver. "Therefore, this signifies the association of plasma Fgf21 with liver cancer-related signalling." (PMID 27470139, 2016). "The close relationship between the liver and FGF21 aroused researchers' attention to the role of FGF21 in liver cancers." (PMID 36263162, 2022). "Accumulated data gave us a relatively deeper understanding of the FGF21-liver cancer axis compared to other cancers." (PMID 36263162, 2022). "Notably, FGF21 is found to be overexpressed in liver cancer, and non-small cell lung cancer, decreased in prostate cancer and pancreatic cancer, and lacking in thyroid cancer." (PMID 38238320, 2024). "Also, another study mentioned that FGF21 was increased in liver cancer and regeneration after partial hepatectomy in a genetic model mouse." (PMID 36457562, 2022). "This may show that the early rise in FGF21 expression can indicate its protective role of it and the late decrease in expression of FGF21 may refer to chronic hepatic disorders comprising liver cancer." (PMID 36457562, 2022). "Further studies will be needed to find the exact role of the FGF21 in liver cancers." (PMID 36457562, 2022). "Consistent with genetic alterations in genes that result in liver cancer, genetic deficiency that causes metabolic perturbations without tumorigenesis in the livers also induced hepatic FGF21 expression." (PMID 23590285, 2013). "The mitokines FGF21 and GDF15 are upregulated during UPRmt and their levels are positively correlated with liver cancer development, progression, and metastasis." (PMID 34440674, 2021).
Myocardial fibrosis (9 papers, 2021 to 2025). "The coordinated reduction of MMP-2, MMP-9 and fibroblast growth factor 21 (FGF21) incurred by resveratrol results in an advance of myocardial fibrosis induced by alcohol." (PMID 36615832, 2022). "Aside from laboratory data, clinical research reveals the indicative potential of FGF21 in myocardial fibrosis as well." (PMID 35677107, 2022). "In the process of myocardial fibrosis, FGF21 retards the fibrosis progression by regulating glucose and lipid metabolism and alleviating inflammatory response and antioxidative stress." (PMID 35677107, 2022). "Results revealed that, compared to WT controls, liver-specific SIRT5-overexpressing mice exhibited markedly reduced MI area and degree of myocardial fibrosis, accompanied by significantly elevated levels of secreted fibroblast growth factor 21 (FGF21) in the circulation." (PMID 41260100, 2025). "Clinical studies have noticed that FGF21 expression is increased in myocardial fibrosis patients." (PMID 35677107, 2022). "In conclusion, these facts suggest that FGF21 therapy could play a protective role in the development of myocardial fibrosis." (PMID 35677107, 2022). "In Fgf21 knockout mice, myocardial fibrosis worsened after myocardial injury." (PMID 34830222, 2021). "It signals that FGF21 may serve as a brand-new biomarker in evaluating myocardial fibrosis." (PMID 35677107, 2022). "Increased expression of FGF-21 has been shown to inactivate the TGF-β1-Smad2/3-MMP2/9 signaling pathway, thereby mitigating myocardial fibrosis, oxidative stress, and cell apoptosis." (PMID 40799939, 2025). "In contrast, exercise has been found to increase Fibroblast growth factor 21 (FGF21) protein expression, inactivate the TGF-β1-Smad2/3-MMP2/9 signaling pathway, reduce myocardial fibrosis, oxidative stress and apoptosis, and finally improve cardiac function in MI mice." (PMID 40520009, 2025).
prediabetes (9 papers, 2015 to 2025). "The association between baseline FGF21/adiponectin ratio and new-onset diabetes and incident prediabetes was evaluated using multiple logistic regression analysis." (PMID 34321008, 2021). "Increased circulating FGF21 levels have been reported in people with prediabetes and T2D, which may be a consequence of metabolic imbalance and/or FGF21 resistance." (PMID 40171198, 2025). "FGF21/adiponectin ratio was a predictor of incident prediabetes (OR 1.185 [95% CI 1.026–1.369], p = 0.021) independent of traditional risk factors, whereas FGF21 and adiponectin alone did not significantly predict incident prediabetes (both p > 0.05)." (PMID 34321008, 2021). "Notably, a high FGF21/adiponectin ratio level was also associated with an increased risk of incident prediabetes among subjects with NGT, while neither FGF21 nor adiponectin were independent predictors of incident prediabetes." (PMID 34321008, 2021). "Moreover, FGF21/adiponectin ratio predicted incident prediabetes (odds ratio, 1.185; p = 0.021) while neither FGF21 nor adiponectin were independent predictors of incident prediabetes (both p > 0.05)." (PMID 34321008, 2021).
acute pancreatitis (8 papers, 2013 to 2025). An acute inflammatory process that leads to necrosis of the pancreatic parenchyma. "The aim of this study was to define an association between FGF21 and the course and resolution of acute pancreatitis in humans." (PMID 27832059, 2016). "In acute pancreatitis mice, knockdown of FGF21 exacerbated inflammatory response and fibrosis, and restoration of FGF21 attenuated inflammation and fibrosis." (PMID 40881124, 2025). "Maximum FGF21 levels were significantly greater than baseline levels for acute pancreatitis subjects (1733 vs. 638 pg/mL, P = 0.003)." (PMID 27832059, 2016). "Active FGF21 levels were analyzed in those samples containing the highest and lowest total FGF21 levels for each acute pancreatitis subject." (PMID 27832059, 2016). "Maximum FGF21 in acute pancreatitis subjects was significantly greater than the highest FGF21 values in controls (1733 vs. 322 pg/mL, P = 0.0002)." (PMID 27832059, 2016). "Baseline FGF21 levels in our acute pancreatitis subjects are comparable to those reported in other studies." (PMID 27832059, 2016). "To assess the possibility that FGF21 is released from the pancreas during acute injury in humans, we measured circulating FGF21 in subjects with acute pancreatitis over the course of their disease." (PMID 27832059, 2016). "We observed that acute pancreatitis subjects had significantly increased peak circulating FGF21 values compared to healthy controls." (PMID 27832059, 2016). "In contrast to the average FGF21 levels in subjects with acute pancreatitis, average FGF21 levels in this cohort of control subjects remained quite stable (range 225.3 ± 38.1 to 271.2 ± 52.3, P = ns)." (PMID 27832059, 2016). "Fold increases in FGF21 were significantly greater in acute pancreatitis subjects than the fold difference seen in healthy subjects (4.7 vs. 2.0, P = 0.01)." (PMID 27832059, 2016). "Maximum FGF21 levels for the acute pancreatitis subjects were significantly greater than baseline levels (1733 vs. 638 pg/mL, P = 0.003)." (PMID 27832059, 2016). "In contrast to our findings, FGF21 levels in acute pancreatitis subjects in this report declined between days one and four of hospitalization." (PMID 27832059, 2016). "Our study demonstrates that, in subjects with acute pancreatitis, circulating levels of FGF21 rise substantially and peak around the time of return to oral intake." (PMID 27832059, 2016). "Maximum FGF21 was significantly greater than baseline FGF21 in acute pancreatitis subjects and significantly greater than levels seen for healthy controls." (PMID 27832059, 2016). "Our results are therefore consistent with these results in the fact that FGF21 can be considered as a marker of the presence and also the severity of cellular injury present in situations of inflammation such as acute pancreatitis, SIRS, and septic shock." (PMID 23999826, 2013). "Nonetheless, the finding of a rise of FGF21 in acute pancreatitis is consistent." (PMID 27832059, 2016). "We speculate that the rise in serum FGF21 reflects a potential role in disease recovery, but more studies are needed to elucidate the precise role of FGF21 in acute pancreatitis." (PMID 27832059, 2016). "Our results demonstrate that serum FGF21 rises significantly in humans with acute pancreatitis." (PMID 27832059, 2016). "Fibroblast growth factor 21 (FGF21), a metabolic hormone with pleiotropic effects on glucose and lipid metabolism and insulin sensitivity, alleviates the process of acute pancreatitis (AP)." (PMID 32233059, 2020). "As subjects did not present at a uniform time during the course of acute pancreatitis, we arbitrarily designated a subject’s “baseline” FGF21 level as the lower value of either the first or last measured FGF21 level during hospitalization." (PMID 27832059, 2016).
atrial fibrillation (8 papers, 2016 to 2024). A disorder characterized by an electrocardiographic finding of a supraventricular arrhythmia characterized by the replacement of consistent P waves by rapid oscillations or fibrillatory waves that vary in size, shape and timing and are accompanied by an irregular ventricular response. "Here, we found that Fgf21 administration attenuated the inducibility of atrial fibrillation/atrial tachycardia (AF/AT), improved epicardial conduction velocity in the mice atria." (PMID 34708083, 2021).
Hepatitis (8 papers, 2013 to 2025). Inflammation of the liver. "Further studies are needed to see if FGF21-pathway manipulation can be therapeutic for feline hepatic lipidosis." (PMID 36756310, 2023). "We also showed that overexpression of FGF21 reduced inflammation and infiltration of immune cells into the liver upon Con A-induced hepatitis." (PMID 32793588, 2020). "There results demonstrated that FGF21 is a protective factor in Con A-induced hepatitis, although the detailed mechanism needs to be further investigated in the future." (PMID 32793588, 2020).
liver dysfunction (8 papers, 2013 to 2025). "We aimed to evaluate the ChREBP–PPARα–FGF21 axis in relation to metabolic liver dysfunction in MHO and MUL individuals." (PMID 41373582, 2025). "Elevated FGF-21 levels, particularly in obese MASLD, indicate its role as a marker of metabolic stress associated with liver dysfunction." (PMID 39910885, 2025). "Recent research highlights the role of adipose tissue in this process, with chronic alcohol intake inducing inflammation, adipose tissue lipolysis, and increase in FGF21 expression contributing to liver dysfunction through an increase in NEFA circulation." (PMID 40381698, 2025). "This study highlights the diagnostic potential of FGF-21 in adolescents with MASLD, particularly for understanding metabolic and liver dysfunction in pediatric populations." (PMID 39910885, 2025). "Similarly, evaluation in a state of severe, advanced fibrosis would be needed; as one surpasses a certain threshold of liver dysfunction, it would be reasonable to think that FGF-21 production may be impaired." (PMID 37999215, 2023).